CXCL13 (C-X-C motif chemokine ligand 13)
Diseases named in the same sentence as CXCL13 in open-access papers (continued):
Sharing a sentence is not in itself a finding about the gene and the disease.
pancreatic cancer (15 papers, 2021 to 2025). "In addition, CXCL13 has been suggested as a crucial pancreatic B-cell chemoattractant associated with proneoplastic functions in a Kras-driven pancreatic cancer model." (PMID 36077611, 2022). "In this paper, we present a strategy for engineering CD34+ cells to derive mDCs, overexpressing CD93, CD40L, and CXCL13, followed by antigen pulsing for enhanced targeting of pancreatic tumors." (PMID 40733726, 2025). "In pancreatic cancer, co-injecting CXCL13 and CCL21 into the tumors of a murine model drove TLS neogenesis and markedly enhanced the anti-tumor effects of chemotherapy." (PMID 41457151, 2025). "highlighted in their study that CXCL13 plays a significant role in promoting the recruitment of disseminated pancreatic cancer cells expressing CXCR5 to the liver, thereby inducing the growth of liver metastases." (PMID 38343537, 2024). "Follicular helper T cells can promote an immunoactive pancreatic cancer microenvironment by secreting CXCL13 and IL-21." (PMID 35468838, 2022). "In pancreatic cancer, CXCL13 signaling participates in the establishment of the pro-oncogenic microenvironment by recruiting tumor-associated B cells." (PMID 34947813, 2021). "Indeed, rmCXCL13 could recruit CD8+ T cells and B cells and thus, control tumor growth, which further proved that Tfh cells can remodel the anti-tumor microenvironment function through CXCL13 in pancreatic cancer." (PMID 34359579, 2021). "In this study, Hu-PBMC mice bearing orthotopic pancreatic tumors were used to evaluate the therapeutic efficacy of our allogeneic DC treatment platform utilizing a lentiviral vector carrying CD93, CD40L, and CXCL13 with tumor-specific antigen pulsing." (PMID 40733726, 2025). "For example, overexpression of ETV4 has been shown to activate the CXCL13/CXCR5 axis, promoting pancreatic cancer metastasis, and ETV4 expression serves as an independent prognostic factor influencing patient survival." (PMID 40469297, 2025). "In KrasG12D-harboring pancreatic ductal adenocarcinoma (PDAC), CXCL13 expression by stromal fibroblasts enhances the infiltration of IL-35 producing B cells into the TME, which potentiates the expansion of pancreatic cancer cells." (PMID 34947813, 2021). "The murine KrasG12DHif1αKO model of pancreatic cancer exhibits an abundant expression of CCL19, CCL20, CCL21, CXCL12, and CXCL13, all of which mediate Breg migration and infiltration into tumor tissue to promote pancreatic tumorigenesis." (PMID 34947813, 2021). "Other examples include T cells engineered to express the chemokine receptor CXCR5 to improve migration in CXCL13 rich lung as well as head and neck cancer microenvironments, and CXCR6 expression that improved migration and function in hypoxic CXCL16-rich pancreatic tumor milieus." (PMID 41181132, 2025). "elucidated that intratumoral injection of CXCL13 and CCL21 could induce TLSs formation in the orthotopic model of pancreatic tumor, resulting in a better therapeutic effect of gemcitabine." (PMID 36420257, 2022).
AIDS (14 papers, 2010 to 2025). A syndrome resulting from the acquired deficiency of cellular immunity caused by the human immunodeficiency virus (HIV). "Increased serum/plasma levels of molecules involved in B-cell activation, among which soluble (s)CD23, sCD27, sCD30, sCD44, and CXCL13, have been associated with the development of acquired immune deficiency syndrome (AIDS)-related BCL2–7." (PMID 32796953, 2020). "In HIV-1 infected individuals, plasma CXCL13 levels have been associated with the rate of disease progression to AIDS." (PMID 33732259, 2021). "CXCL13 has also been evaluated as a potential biomarker for early diagnosis of AIDS-associated non-Hodgkin B-cell lymphoma." (PMID 33732259, 2021). "In addition, plasma levels of CXCL13, IL-6 and IL-10 were potential markers for treatment outcomes and survival of patients with AIDS-associated non-Hodgkin lymphoma (NHL)." (PMID 33732259, 2021). "The studies reviewed here point to CXCL13 as a potential general biomarker for GC activity of particular interest in HIV/AIDS." (PMID 33732259, 2021). "Several AIDS-NHL cell lines, including the AIDS-BL cell line, 2F7, also demonstrated chemotaxis towards CXCL13 in vitro." (PMID 23936541, 2013). "For these studies, we examined CXCR5 and CXCL13 expression in tissue arrays containing sections of primary specimens of AIDS-NHL from different subjects, using immunohistochemistry." (PMID 21490903, 2010). "CXCL13 levels in the AIDS-NHL group were also ~2.5× greater than levels in the HIV(+) group, and ~7× greater than levels in the HIV(−) group; these results were statistically significant." (PMID 21490903, 2010). "The mean CXCL13 level seen in the AIDS-NHL group (158 pg/mL, SD = 153) was ~50% higher than in the AIDS control group (98.4 pg/mL, SD = 70.9, P = .02)." (PMID 21490903, 2010). "In these studies, we examined CXCL13 levels in AIDS-NHL subjects, using serum obtained at a mean time of 8.2 months prior to diagnosis." (PMID 21490903, 2010). "In summary, we have demonstrated an association between expression of the chemokine, CXCL13, and its receptor, CXCR5, and AIDS-NHL." (PMID 21490903, 2010). "In these studies, we examined expression of CXCR5 and CXCL13 on the AIDS-NHL cell lines, 2F7 (Burkitt subtype) and R (DLBCL subtype)." (PMID 21490903, 2010). "The ability of the AIDS-NHL cell lines to respond to CXCL13 was examined using standard migration assays." (PMID 21490903, 2010). "CXCL13 levels in the AIDS-NHL group were even more highly elevated when compared to the HIV(+)/non-AIDS and HIV-seronegative groups." (PMID 21490903, 2010). "Given the fundamental importance of CXCL13 in adaptive immune responses, we have reviewed the literature of CXCL13 in HIV/AIDS, focusing on its association with disease progression, the generation of broadly neutralizing antibodies (bnAbs) and HIV-associated B cell lymphoma." (PMID 33732259, 2021). "Given that AIDS-related NHL is frequently related with EBV infection, this CXCL13/CXCR5 interaction might be present in ENKTL like AIDS-related NHL." (PMID 25966773, 2015). "Recently, we showed that serum levels of CXCL13 were elevated in preceding AIDS-NHL diagnosis." (PMID 23936541, 2013). "The marked elevations in tumor cell CXCR5 expression and in murine CXCL13 levels seen in the model may potentially identify an important link between tumor-interacting histiocytes and tumor cells in AIDS-BL." (PMID 23936541, 2013). "Both AIDS-NHL cell lines used in our studies demonstrated chemotaxis towards CXCL13." (PMID 21490903, 2010). "If so, CXCL13 could potentially prove to be a useful biomarker for early detection of AIDS-NHL, for determining burden of disease, and for determining prognosis following chemotherapy." (PMID 21490903, 2010). "Third, it seems possible that CXCL13 could be directing movement and/or metastasis of AIDS-NHL cells in the body." (PMID 21490903, 2010).
AIDS (continued). "Several mechanisms, which are not necessarily mutually exclusive, appear possible: first, it seems plausible that CXCR5 and CXCL13 could be playing a role in the initial development of AIDS-NHL." (PMID 21490903, 2010). "Furthermore, CXCR5 and/or CXCL13 were expressed in most primary AIDS-NHL tumor specimens." (PMID 23936541, 2013). "CXCL13/CXCR5 are expressed, and may play a role, in some non-AIDS-associated B cell tumors." (PMID 21490903, 2010). "Thus, these combined data indicate that CXCL13 is frequently expressed in AIDS-NHL." (PMID 21490903, 2010). "CXCL13/CXCR5 are expressed in AIDS-NHL and could potentially be involved in its biology." (PMID 21490903, 2010). "Thus, further study of CXCR5 and CXCL13 expression and function in AIDS-NHL, and in non-AIDS-associated NHL, could ultimately reveal some unique differences between the pathogenesis of AIDS-related and non-AIDS-related B cell lymphomas." (PMID 21490903, 2010). "Significant associations were observed between baseline plasma levels of CD20+ EVs and baseline plasma levels of prognostic biomarkers of AIDS-NHL: sCD27, CXCL13, sIL-2Rα/sCD25, sTNF-RII, sCD163, IL-18, LBP, and EndoCab IgM." (PMID 40646161, 2025). "CCL8, CXCL13, and IL-1RA levels were elevated in patients with active, but not inactive, SLE versus HC, as well as in patients with SLE versus other AIDs, and the levels of these cytokines correlated with SLE disease activity." (PMID 38098483, 2023). "Specifically, CCL8, CXCL13, and IL-1RA levels were elevated in patients with active, but not inactive, SLE versus HC, as well as in patients with SLE versus other AIDs." (PMID 38098483, 2023). "In this review, we address the role of CXCL13 in HIV-1 infected individuals with regard to GC formation, generation of broadly neutralizing antibodies after infection and vaccination, and AIDS-related B cell lymphoma." (PMID 33732259, 2021). "The expression or function of CXCL13 and CXCR5 was examined on primary AIDS-NHL specimens or AIDS-NHL cell lines." (PMID 21490903, 2010). "Future studies will be needed to more fully determine the feasibility of using CXCL13 as a biomarker for AIDS-NHL, as well as to define the function of CXCL13 and CXCR5 in the pathogenesis of AIDS-NHL." (PMID 21490903, 2010). "Furthermore, CD20+ EVs showed significant positive correlations with potential prognostic biomarkers of AIDS-NHL29,30,40,41 at baseline: sCD27, CXCL13, sIL-2Rα/sCD25, sTNF-RII, sCD163, IL-18, LBP, and EndoCab IgM." (PMID 40646161, 2025). "In the present study, we examined how baselinies plasma levels of CD20+ extracellular vesicles (EVs) relate to these previously characterized biomarkers of AIDS-NHL, such as IL-10, CXCL13, IL-10, BAFF, sCD14, sTNF-RII, sIL-2Rα/sCD25, IL-18, and CCL12-MCP-129–31." (PMID 40646161, 2025). "Defining associations between these B-cell populations and matched serum levels of CXCL13 would be important as we and others have shown that the levels of CXCL13 are significantly elevated in PLWH prior to an AIDS-NHL diagnosis and before and after the initiation of treatment of AIDS-NHL patients." (PMID 39324141, 2024). "Additionally, serum levels of CCL8, CXCL13, and IL-1RA were higher in patients with SLE compared with patients with other AIDs, and they correlated with global SLE disease activity." (PMID 38098483, 2023). "CXCL13 represents a novel marker of systemic immune activation during early and chronic HIV infection and may be used to predict the development of non-AIDS events." (PMID 30846990, 2019). "A second possibility is that the CXCL13 and/or CXCR5 could be directly promoting AIDS-NHL tumor growth, or performing some other tumor-promoting functions, such as inhibiting apoptosis or enhancing angiogenesis." (PMID 21490903, 2010). "The receptor for CXCL13, CXCR5, appears to be commonly expressed in AIDS-NHL, as well." (PMID 21490903, 2010). "In this report, we define the expression and function of CXCL13 and CXCR5 in AIDS-NHL." (PMID 21490903, 2010).
AIDS (continued). "Our studies do suggest that autocrine interactions could be occurring in AIDS-NHL, as some tumor cells appeared to express both CXCR5 and CXCL13 in both the immunohistochemistry and AIDS-NHL cell line studies (Section 3)." (PMID 21490903, 2010). "AIDS-NHL cell lines expressed CXCR5 and showed chemotaxis towards CXCL13." (PMID 21490903, 2010). "All primary AIDS-NHL specimens showed CXCR5 expression and most also showed CXCL13 expression." (PMID 21490903, 2010). "All AIDS-NHL tumors showed some degree of CXCR5 expression, and most (22/24) expressed CXCL13." (PMID 21490903, 2010). "Although our studies show that both CXCL13 and CXCR5 are commonly expressed in AIDS-NHL, future studies will be needed to determine more exactly what roles these molecules may be playing in these cancers." (PMID 21490903, 2010). "The frequent expression of CXCL13 in the AIDS-NHL tumor specimens (Section 3) raises the possibility that the developing tumors themselves are a source of the elevated serum CXCL13 levels seen preceding diagnosis in the AIDS-NHL group." (PMID 21490903, 2010). "Additionally, the CXCR5 on the AIDS-NHL cell lines appeared to be functional, as both cell lines showed chemotaxis towards CXCL13." (PMID 21490903, 2010). "Furthermore, CXCL13 levels correlated with sCD44 levels in the AIDS-NHL group (R = 0.31, P = .04), but not in the AIDS control group (R = 0.07; P = .7, data not shown); we previously showed that sCD44 levels are elevated prior to AIDS-NHL development." (PMID 21490903, 2010). "Finally, by demonstrating temporal correlation of CXCL13 plasma levels with progression of HIV infection, CXCL13 was proposed as a biomarker of systemic immune activation during HIV infection that may serve to predict AIDS-defining events." (PMID 31354634, 2019). "Second, many primary AIDS-NHL specimens, of both the Burkitt and DLBCL subtypes, showed expression of CXCL13.Third, as noted in (Section 3), the AIDS-Burkitt cell line, 2F7, expressed low levels of CXCL13 after it had been growing in culture for several months (not shown)." (PMID 21490903, 2010).
B-cell lymphoma (14 papers, 2010 to 2025). "Recent evidence also indicates that, apart from inflammatory CNS diseases, CSF CXCL13 may be of diagnostic and prognostic relevance in B cell lymphoma of the CNS." (PMID 20700489, 2010). "Top proteins that were consistently associated with B-cell lymphoma across the EPIC, ARIC and UK Biobank cohorts included: CXCL13, sCD23, FCRL1, FCRL3, SEMA7A, CD72, CD48, LY9 and VCAM1." (PMID 40894013, 2025). "We demonstrated superior brain delivery via MPC nanoencapsulation, tumor targeting through CXCL13, and complete elimination of brain-metastasized B-cell lymphoma by releasing RTX in the brain." (PMID 37920826, 2023). "CXCL13 is the agonist of Tfh defining marker CXCR5, and its serum levels have been proven to predict B-cell NHL risk in HIV+ individuals." (PMID 37297008, 2023). "If the release of CXCL13 could occur in vivo, it could promote the onset of B cell lymphomas, malignancies that indeed more frequently arise in patients suffering of IBD." (PMID 37797746, 2023). "For instance, we encapsulated the therapeutic antibody rituximab (RTX) that targets CD20 of B-cell lymphoma into MPC nanocapsules with degradable crosslinkers, followed by conjugation of CXCL13 as a ligand (nRTXCXCL13) on the surface to target B-cell lymphomas." (PMID 37920826, 2023). "CXCL13, the ligand for CXCR5, is overexpressed in salivary glands of pSS patients, and increased expression of CXCL13 is associated with increased B cell hyperactivity, and development of B cell lymphoma." (PMID 36505431, 2022). "It should be noted that CXCR5 and/or CXCL13 have been shown to be associated with several non-AIDS-related B cell lymphomas, including extragastric lymphoma of mucosa-associated lymphoid tissue (MALT) and follicular lymphoma." (PMID 21490903, 2010). "Such an overproduction of CXCL13 may not necessarily be occurring prior to the initiation of tumor development in otherwise healthy subjects who develop B cell lymphoma outside of the context of HIV infection." (PMID 21490903, 2010). "CXCL13 and its receptor, CXCR5, are required for B-cell homing to follicles in lymph nodes, suggesting that aberrant CXCL13 expression may be involved in the pathogenesis of B-cell lymphoma through abnormal chemotaxis of B-cells to tissues or abnormal B-cell activation." (PMID 30873511, 2018).
bladder cancer (14 papers, 2020 to 2025). "When ARID1A gene mutation and high expression of CXCL13 are present in bladder cancer, the sensitivity to immune checkpoint therapy is increased." (PMID 39779467, 2025). "In the domain of bladder cancer research, a recent discovery has unveiled that the expression of CXCL13 is significantly associated with both PFS and OS in patients undergoing immune checkpoint blockade (ICB) therapy." (PMID 39198425, 2024). "CXCL13 is associated with better survival after immunotherapy in patients with advanced bladder cancer and can predict ICI response in advanced bladder cancer patients." (PMID 38155221, 2023). "Goswami and colleagues have recently shown that ARID1A mutation in combination with immune cytokine CXCL13 expression predicts response to immune checkpoint inhibitors in metastasized bladder cancers." (PMID 33227989, 2020). "In bladder cancer, data from the CheckMate-275 and IMvigor210 trials demonstrated that patients with ARID1A mutations and high CXCL13 expression had favorable outcomes following ICI treatment." (PMID 40406143, 2025). "Interestingly, in a study on advanced-stage bladder cancer, CXCL13 was demonstrated as a surrogate marker for tumor TLS." (PMID 39544934, 2024). "The bias between either GZMK+ or GZMB+ cytotoxic CD4+ T cells has been observed in bladder cancer and CD4+CXCL13+ TFH-like cells in endometrial cancer." (PMID 41030456, 2025). "Similarly, another study revealed a prognostic and predictive role of CXCL13-mediated TLSs in bladder cancer patients treated with ICI and favorable outcomes, but they did not evaluate CXCL13+ cell density potential role in different compartments." (PMID 38398098, 2024).